CRP (C-reactive protein)
Diseases named in the same sentence as CRP in open-access papers (continued):
Sharing a sentence is not in itself a finding about the gene and the disease.
atherosclerosis (continued). "Inflammation with elevated high-sensitive C-reactive protein (hs-CRP) is involved in both sudden cardiac death and atherosclerosis, and decreased heart rate variability (HRV) is a predictor of both sudden cardiac death and atherosclerosis." (PMID 23573421, 2013). "Experimental models of atherosclerosis display upregulated inflammatory markers, including C-reactive protein (CRP), which is present in atherosclerotic lesions." (PMID 24077237, 2013). "The aim of this study was to investigate the effect of C-reactive protein/oxidised low-density lipoprotein/β2-glycoprotein I (CRP/oxLDL/β2GPI) complex on atherosclerosis (AS) in diabetic BALB/c mice." (PMID 23531147, 2013). "As yet the mechanism linking circulating levels of CRP within the reference range to the pathogenesis of atherosclerosis and other chronic disease is uncertain." (PMID 23391158, 2013). "Clinically, the reduction of CRP-induced IL-6 production with E2 pre-treatment shown by our result could indicate a key role of this hormone in the prevention or reduction of cytokine inflammatory response implicated in the development and maintenance of atherosclerosis." (PMID 23111890, 2013). "C-reactive protein, elevated in EOA, is associated with atherosclerosis and is predictive of future ischemic events." (PMID 24711757, 2013). "Although CRP levels were within the normal range in our sample of TS patients, the distinct but significant increase compared to controls could point to a latent underlying inflammatory process, similar to the role of high sensitivity CRP in the pathogenesis of atherosclerosis." (PMID 22471395, 2012). "For example, the elevated level of C-reactive protein (CRP) is indicative of an inflammatory response and it is now widely accepted as a marker of atherosclerosis." (PMID 23300770, 2012). "CRP levels in the normal range (<5 mg/L) are known to be predictive of atherosclerosis-related cardiovascular events such as myocardial infarction or stroke, with moderate risk at levels >1 mg/L and high risk at levels >3 mg/L." (PMID 22479353, 2012). "However causality of CRP on atherosclerosis remains unclear." (PMID 22505888, 2012). "Since hypercholesterolemia is a major participator in the inflammatory process of atherosclerosis, several in vitro and in vivo studies have been showed the increased level of CRP in hypercholesterolemic animals and patients." (PMID 23497719, 2012). "Recent human studies demonstrated that elevated CRP levels more likely is a marker for the extent of atherosclerosis or for the inflammatory activity of atherosclerotic plaques, and effectively exclude that genetically elevated CRP cause CHD." (PMID 23162475, 2012). "Relationships have consistently been identified among atherosclerosis and cardiovascular disease with greater levels of C-reactive protein (CRP), TNF-α, and IL-6." (PMID 24052871, 2012). "C-reactive protein level has been established as a determinant of the inflammatory process in atherosclerosis." (PMID 22836155, 2012). "Elevated concentrations of proinflammatory cytokines such as TNFα, and CRP play a significant role in the genesis of atherosclerosis and in plaque instability." (PMID 22745783, 2012). "The pro-inflammatory effects of CRP via CD40–CD40L signaling pathways also involved in the pathogenesis of atherosclerosis." (PMID 23162475, 2012). "Low levels of adiponectin are associated with higher levels of highly-sensitive C-reactive protein (hs-CRP) and IL-6, two inflammatory mediators that are involved in the initiation and progression of atherosclerosis and renal disease." (PMID 22567283, 2012). "CRP has been found to correlate with the degree of subclinical atherosclerosis, measured by carotid artery intima-media wall thickness, and the presence of clinically evident cardiovascular disease in adults with rheumatoid arthritis." (PMID 22933832, 2012).
atherosclerosis (continued). "It is well accepted that atherosclerosis is based on a chronic low-grade systemic inflammation as indicated by moderately increased levels of markers of inflammation, that is, cytokines, C-reactive protein, or fibrinogen." (PMID 22110915, 2012). "CRP is not only an indicator for generalized inflammatory reaction, but also a mediator involved in the pathogenesis of atherosclerosis." (PMID 22933832, 2012). "The consequences of CRP and ROS in platelet activation and thrombus formation, as well as atherosclerosis, are key features of atherothrombosis." (PMID 23162475, 2012). "C-reactive protein, determined by high-sensitivity techniques, is the most widely studied marker of inflammation in the field of atherosclerosis." (PMID 22836155, 2012). "The link between inflammation and atherosclerosis is strongly supported by the finding of a direct correlation between CRP and ESR with the IMT in the present setting." (PMID 23036698, 2012). "Measures of carotid and femoral artery atherosclerosis according to CRP tertile groups in the Bruneck Study." (PMID 22319633, 2012). "Indeed, several reports have suggested that CRP could be associated with atherosclerosis through various mechanism such as 1) release of reactive oxygen species, 2) increased expression of adhesion molecules, 3) induction of foam cell formation, and 4) destabilization of plaque." (PMID 22583484, 2012). "The role of CRP, in atherosclerosis and its effects on patients' prognosis and mortality after CABG have been investigated." (PMID 22811936, 2012). "Markers of inflammation, such as pro-inflammatory cytokines and C-reactive protein (CRP), are involved in the development of atherosclerosis and CRP predicts cardiovascular events independently of other CV risk factors." (PMID 21241491, 2011). "It seems therefore that postprandial CRP concentrations, which were increased 2-fold compared to fasting concentrations, react strongly to vascular damage and/or atherosclerosis." (PMID 21756316, 2011). "A strong correlation was observed between postprandial plasma CRP and aorta fatty streak area (R2 = 0.95, p < 0.001), suggesting that postprandial CRP is a biomarker for atherosclerosis in this diabetic pig model." (PMID 21756316, 2011). "Regardless of the mechanism, systemic inflammation seems to be the basis to explain the nature of the connection between chronic infection and atherosclerosis, in which CRP is a reliable marker of acute phase response to infection or inflammation." (PMID 28348657, 2011). "There were statistically significant reductions in the levels of ICAM-1, VCAM-1 and CRP at the end of treatment with water extract in group 500 mg/kg compared to atherosclerosis group." (PMID 21214952, 2011). "Treatment with atorvastatin lead not only to the decrease of serum lipids and CRP levels, but also to the limitation of atherosclerosis progression as assessed by MDCT-based calcium scoring." (PMID 21774822, 2011). "We examined the association of CRP with EDNO-dependent vasomotor function and subclinical measures of atherosclerosis and arteriosclerosis in patients with raised CRP resulting from rheumatoid arthritis (RA)." (PMID 20436910, 2010). "In an analysis of data from nearly 6000 participants in the Multi-Ethnic Study of Atherosclerosis (MESA), consumption of nuts and seeds was inversely associated with levels of inflammatory markers, C-reactive protein (CRP), interleukin-6 (IL-6) and fibrinogen." (PMID 22254047, 2010). "In recent years CRP has also come up as a leading biological marker of atherosclerosis, with serum CRP concentrations, even at very low levels, predicting the risk of acute myocardial infarction or stroke in apparently healthy individuals." (PMID 20920269, 2010). "It has been suggested that CRP itself contributes to the development of atherosclerosis, as it exerts direct proinflammatory effects on endothelial cells." (PMID 20920173, 2010).
atherosclerosis (continued). "C-reactive protein (CRP) is increasingly implicated as a candidate linking conventional risk factors and atherosclerosis." (PMID 20137842, 2010). "In prospective studies, markers of inflammation such as C-reactive protein (CRP) and fibrinogen have been found to be predictive of atherosclerosis and an increased risk of CVD events." (PMID 20078877, 2010). "CRP was independently associated with CVD (cardiovascular diseases) after adjusting for the Framingham risk factors, atherosclerosis, anthropometric measurements, and ethnicity (OR = 1.03 for a 0.1-increase in CRP; P = 0.02)." (PMID 21062475, 2010). "C-reactive protein (CRP), an inflammation marker, induces pro-inflammatory cytokines through NF-κB and contributes to atherosclerosis in endothelial cells." (PMID 20565944, 2010). "In the context of atherosclerosis, concentrations of C-reactive protein (CRP) and fibrinogen and the count of leukocytes in blood have been investigated most extensively." (PMID 21188207, 2010). "Inflammation is an important component in all stages of atherosclerosis and interestingly, IL-17 has recently been reported to stimulate expression of CRP in hepatocytes and in coronary artery smooth muscle cells." (PMID 19240794, 2009). "This relationship between inflammation and atherosclerosis make CRP a potential marker for prognosis after vascular events and a potential predictor of future vascular events." (PMID 19400931, 2009). "Serum CRP is an important marker of vascular inflammation and can be used to predict atherosclerosis." (PMID 18289377, 2008). "Several studies have suggested CRP as biomarker for cardiovascular and cerebrovascular diseases; however, this protein also seems to be a mediator of atherosclerosis." (PMID 18764931, 2008). "In recent years CRP has come to prominence as a biological marker of atherosclerosis, with serum CRP concentrations, even at very low levels, predicting the risk of acute myocardial infarction or stroke in apparently healthy individuals." (PMID 18560524, 2008). "CRP represents one of the strongest independent predictors of symptomatic atherothrombosis and vascular death and predicts progression of atherosclerosis." (PMID 18764931, 2008). "We investigated the effect of etoricoxib on four biomarkers of CV risk, i.e., CRP, LDL-C, homocysteine, and fibrinogen, implicated in the genesis of clinical CV disease with roles in atherosclerosis, thrombosis, and inflammation." (PMID 20157362, 2008). "Accumulating evidence also suggests that atherosclerosis represents a chronic inflammatory process and inflammatory markers like CRP and fibrinogen, homocysteine provide an adjunctive method for global assessment of cardiovascular risk." (PMID 17919323, 2007). "As an upstream pro-inflammation marker, IL-6promotes expression of CRP gene in the liver, and elevated level is a strongpredictor of atherosclerosis and mortality in dialysis patients." (PMID 18288267, 2007). "These high-sensitivity CRP (hs-CRP) assays have led to increasing use of this protein in the study of the inflammatory nature of many chronic diseases such as atherosclerosis." (PMID 19690638, 2007). "This discrepancy leads to findings of other complementary predictors for atherosclerosis and heart failures including C-reactive protein (CRP), troponin, and B-type natriuretic peptide." (PMID 17042957, 2006). "This would suggest their greater utility in being more accurate markers of disease, particularly given C-reactive protein's increasingly apparent role in the pathogenesis of atherosclerosis." (PMID 15974805, 2005). "Previously believed to be synthesized by the liver, recent evidence suggests that C-reactive protein is also produced at the site of atherosclerosis by smooth muscle cells." (PMID 15974805, 2005). "Elevated levels of proinflammatory cytokines and CRP play a significant role in the genesis of atherosclerosis and in plaque instability." (PMID 16263508, 2005).
atherosclerosis (continued). "The second phase is characterized by advancing atherosclerosis, with greater impact of inflammation as indicated by an elevated level of plasma C-reactive protein, the result of increased production influenced by interleukin-6." (PMID 15574198, 2004). "First, systemic inflammation, as indicated by elevated CRP and IL-6 levels, may promote both venous remodeling and arterial atherosclerosis." (PMID 40912305, 2026). "CRP is not only a marker of inflammation but can also directly participate in atherosclerosis progression through multiple mechanisms, including promoting monocyte adhesion and chemotaxis, activating the complement system, enhancing oxidative stress, and inducing endothelial dysfunction." (PMID 41607462, 2026). "Chronic systemic inflammation in IBD plays a crucial role in atherosclerosis progression, contributing to CVD risk by promoting endothelial dysfunction, oxidative stress, and macrophage accumulation through elevated markers such as CRP." (PMID 40510678, 2025). "Pro-inflammatory cytokines (IL-6, TNF-α, CRP) → endothelial dysfunction, atherosclerosis." (PMID 40566026, 2025). "Furthermore, it is unclear how well-established decreases in inflammatory markers like erythrocyte sedimentation rate (ESR) and C-reactive protein (CRP) translate into significant decreases in CV events or surrogate indicators of atherosclerosis." (PMID 41018385, 2025). "Elevated levels of inflammatory markers such as interleukin-6 (IL-6) and C-reactive protein (CRP) have been consistently observed in HIV-positive individuals and are strongly associated with endothelial dysfunction, accelerated atherosclerosis, and myocardial injury." (PMID 40787484, 2025). "CRP and IL-6 contribute to both atherosclerosis and kidney damage." (PMID 40376312, 2025). "Elevated serum CRP values are also a biomarker for the progression of subclinical atherosclerosis." (PMID 41010664, 2025). "Studies suggest that cytokines, matrix metalloproteinases, selectins, intracellular adhesion molecules, vascular cell adhesion molecules, C-reactive protein, and fibrinogen are involved in the initiation and progression of atherosclerosis, which influences the onset and development of PAD." (PMID 39898107, 2025). "Additionally, we sought to elucidate the relationship between morning surge and inflammatory markers such as C-reactive protein (CRP) and fibrinogen-to-albumin ratio (FAR), which are associated with heightened atherosclerosis risk." (PMID 40002776, 2025). "This suggests a closer relationship between aortic atherosclerosis lesions and CRP." (PMID 40779499, 2025). "Briefly, CRP induces inflammatory changes in endothelial and smooth muscle cells, contributing to endothelial dysfunction and the progression of atherosclerosis, which in turn facilitates thrombogenesis through the stimulation of macrophage tissue factor biosynthesis." (PMID 39970158, 2025). "Semaglutide may reduce atherosclerosis by lowering inflammation (e.g., C-reactive protein) and improving endothelial function through GLP-1 receptor–mediated nitric oxide production and reduced vascular oxidative stress." (PMID 40732345, 2025). "While CRP is often viewed as an inflammation marker, evidence suggests it may also actively participate in atherosclerosis by modulating endothelial cells, smooth muscle proliferation, and lipid uptake." (PMID 41375908, 2025). "The study of one single cytokine role in atherosclerosis is extremely difficult, seeing that some of these biomarkers induce the activity of others; for example, IL-1 induces IL-6, IL-18, and CRP, for which a combination of cytokines is possibly a better choice." (PMID 41226718, 2025). "To determine whether CRP could be a useful biomarker of stroke etiology, we investigated CRP expression in acute ischemic stroke (AIS) clots from large-artery atherosclerosis (LAA), cardio-embolism (CE) and cryptogenic (Crypt) subtypes." (PMID 39910895, 2025).
atherosclerosis (continued). "HHcy promotes atherosclerosis by driving inflammation, as evidenced by elevated hs-CRP levels, which may lead to lacunar infarction." (PMID 39898976, 2025). "By reducing nitric oxide generation within endothelial cells, increasing expression of endothelial cell adhesion molecules, and monocyte recruitment, CRP promotes the progression and instability of atherosclerosis and thrombosis, thereby increasing individual mortality risk." (PMID 40128977, 2025). "CRP plays a direct role in thedevelopment of endothelial dysfunction and atherosclerosis which supports its strong link to CVD.Doctors widely recognize Troponin I as a highly specific marker because it diagnoses myocardial injury accurately in acute coronarysyndromes according to medical research." (PMID 40978648, 2025). "The observed trend with CRP levels further suggests the atherosclerosis mechanism at play as CRP is a well-established acute phase reactant and biomarker of systemic inflammation, which contributes to the initiation, progression, and destabilisation of atherosclerotic plaques and ultimately CVD." (PMID 40375303, 2025). "Also, in addition to its important role in the progression of atherosclerosis, CRP, as a positive acute-phase reactant, is also an indicator of the inflammatory status that contributes to the aggravation of malnutrition." (PMID 40648869, 2025). "It remains to be proven whether the reductions in CRP or IL-6 achieved with probiotics will translate into fewer cardiac events or slower atherosclerosis progression." (PMID 41156763, 2025). "In patients with T2DM and DPN, Nrg4 levels were negatively correlated with inflammation and oxidative stress markers hs-CRP, 88-iso-PGF2α, and VPT, suggesting that Nrg4 deficiency may trigger the development of atherosclerosis." (PMID 39162358, 2024). "The results of our study suggest that CRP might be an important risk factor that connects ABI and carotid artery stenosis, which are non-invasive indicators of generalized atherosclerosis in T2DM." (PMID 38248862, 2024). "Systemic inflammatory diseases and increased production of CRP may also accelerate premature atherosclerosis, as has been shown in SLE, RA, granulomatosis with polyangiitis, and Takayasu arteritis." (PMID 37788103, 2024). "Similarly, a review assessing associations of dietary patterns with atherosclerosis risk biomarkers (i.e., LDL-C, ApoB, and CRP) in FH patients, found beneficial effects of a healthy dietary pattern combined with an overall healthy lifestyle." (PMID 39525275, 2024). "Additionally, a correlation was found between elevated CRP levels and the incidence of endothelial dysfunction and preclinical atherosclerosis." (PMID 39310576, 2024). "Our results suggest that CRP might be an important risk factor that connects ABI and carotid artery stenosis, which are non-invasive indicators of generalized atherosclerosis in T2DM." (PMID 38248862, 2024). "Moreover, elevated levels of lipoprotein (a) [LP(a)], fructosamine, homocysteine, and C-reactive protein (CRP) have also been reported to further contribute to atherosclerosis in hypothyroid patients." (PMID 39735488, 2024). "Additionally, exercise training reduces inflammation, as evidenced by decreased CRP concentrations in otherwise healthy adults, helping to protect arteries from atherosclerosis and stabilize existing plaques." (PMID 39458547, 2024). "Our study did not identify a significant association between hs-CRP and atherosclerosis, a finding that contrasts with previous research." (PMID 39104857, 2024). "As VEGF, CRP, IL-6 and TNF-R1 are regarded as biomarkers for atherosclerosis this implies that patients in the RA risk group might already have a higher cardiovascular disease risk." (PMID 39012360, 2024). "Furthermore, since atherosclerosis is presumed to be an inflammatory disease, C-reactive protein (CRP), as determined by a highly sensitive immunoassay, has been suggested as a strong predictor of cardiovascular risk." (PMID 39687453, 2024).